UROC1 (urocanate hydratase 1)
Synonyms: FLJ31300; HMFN0320; UROCD
Tractability: PROTAC: ubiquitination databases record sites on it.
Gene: Protein-coding gene on chromosome 3 (126,481,165 to 126,517,777, reverse strand). Ensembl gene ENSG00000159650.
Pathways (Reactome):
Metabolism: Histidine catabolism
Gene Ontology:
Molecular function: protein binding; urocanate hydratase activity
Biological process: L-histidine catabolic process
Cellular component: cytosol
Genetic constraint (gnomAD): Loss-of-function variants: 83 observed, 94.06 expected, observed/expected ratio (o/e) 0.88, 90% interval 0.74 to 1.06. The upper end of that interval is the gene's LOEUF score, 1.06, which puts it in group 4 of 6, group 1 being the genes least tolerant of losing a copy. Missense variants: 885 observed, 934.99 expected, observed/expected ratio (o/e) 0.95, 90% interval 0.89 to 1. Synonymous variants: 361 observed, 370.28 expected, observed/expected ratio (o/e) 0.97, 90% interval 0.89 to 1.06.
Gene-disease validity (ClinGen):
ClinGen rates the evidence that UROC1 causes each of these diseases.
urocanic aciduria (autosomal recessive): Limited. Encephalopathy due to urocanase deficiency is an extremely rare histidine metabolism disorder characterized by urocanic aciduria and other variable manifestations including intellectual deficit and intermittent ataxia in the 4 cases reported to date.
Homologues: Orthologues: chimpanzee UROC1 (99% identical), macaque UROC1 (97% identical), rat Uroc1 (92% identical), mouse Uroc1 (92% identical), rabbit UROC1 (92% identical), guinea pig UROC1 (91% identical), dog UROC1 (89% identical), pig UROC1 (88% identical), tropical clawed frog uroc1 (79% identical), zebrafish uroc1 (76% identical), Caenorhabditis elegans uroc-1 (61% identical).
Diseases named in the same sentence as UROC1 in open-access papers:
UROC1 is named in the same sentence as 5 diseases in open-access papers, as found by Europe PMC text mining. Sharing a sentence is not in itself a finding about the gene and the disease. The quoted sentences say what the papers report.
hepatoblastoma (1 paper, 2008). Hepatoblastoma (HB) is a malignant hepatic tumor and is the most common pediatric liver cancer. "Since human Uroc1 gene is highly expression in hepatoblastoma than in fetal liver, it is possible that Uroc1 is preferentially expressed in liver tumors and thus may serve as a marker." (PMID 18218118, 2008).
cancer (2 papers, 2019 to 2022). A tumor composed of atypical neoplastic, often pleomorphic cells that invade other tissues. "Considering there were few studies about UROC1 in cancer, its special functions in HCC development needed further investigation." (PMID 30755830, 2019). "UROC1 (21%), HAO1 (15%), and SLC5A5 (14%) were the top three mutant genes in human cancers." (PMID 36313638, 2022).
UROC1 also shares sentences with these, for which no sentence is quoted: hepatocellular carcinoma (1 paper); Peri-Implantitis (1); skin cancer (1).